FOXM1 (forkhead box M1)
Diseases named in the same sentence as FOXM1 in open-access papers (continued):
Sharing a sentence is not in itself a finding about the gene and the disease.
cervical carcinoma (continued). "As FOXM1 is a master regulator of cancer cell growth, it is of interest to examine whether increased AMPK activity has any functional impact on FOXM1 in cervical cancer oncogenesis." (PMID 23819460, 2013). "We demonstrated that AMPK activated by either micro-environmental stresses or pharmaceutical AMPK activators could reduce FOXM1 expression through blocking the AKT/FOXO3a signaling pathway, that in turn impaired cervical cancer cell growth." (PMID 23819460, 2013). "However, the mechanism by which FOXM1 increases resistance to paclitaxel in cervical cancer has not been fully elucidated." (PMID 35141332, 2022). "UHRF1 had not previously been linked to FOXM1 or OAC but has been shown to be overexpressed in a wide range of other cancers and consistent with our observations of high levels in late stage OAC, has also been shown to be a marker for tumour aggressiveness in cervical cancer." (PMID 25889361, 2015).
liver cancer (65 papers, 2008 to 2025). An epithelial or non-epithelial malignant neoplasm that arises from the liver. "HBV X protein, that is, HBV promotes the migration and invasion of liver cancer cells by upregulating the expression of FoxM1, causing liver cancer metastasis, ultimately leading to a poor prognosis." (PMID 36159567, 2022). "It was demonstrated that elevated FoxM1 expression associated with miR-34a downregulation has an important function in liver cancer progression." (PMID 32308683, 2020). "Meanwhile, elevated FoxM1 expression associated with miR-34a downregulation plays a crucial role in liver cancer progression." (PMID 32308683, 2020). "Besides, the loss of FXR in obese diabetic mice develops liver cancer through increased cell division cycle 25B (Cdc25b), Cyclin D1, and forkhead box protein M1 (FoxM1)." (PMID 35006466, 2021). "Additionally FOXM1 was shown to be associated with sorafenib drug resistance in liver cancer cells via AKT-CJUN-AP1- FOXM1 signaling." (PMID 33680951, 2020). "It has been reported that FoxM1 can increase CD44 expression via binding with CD44 promoter in human liver cancer cells." (PMID 40050970, 2025). "For example, a cell-penetrating ARF peptide was identified as an inhibitor of FOXM1, it can be utilized as a practical treatment method to reduce proliferation and induce apoptosis in liver cancer cells within mouse tumor models." (PMID 38741782, 2024). "For example, miR‐214 inhibits liver cancer cell proliferation and migration through reducing FOXM1 levels." (PMID 38180276, 2024). "In summation, our radiomics analysis, rooted in a robust methodology and comprehensive feature selection, offers promising models for predicting FOXM1 expression in liver cancer." (PMID 37817774, 2023). "Our results also showed that disruption of IQGAP1/FOXM1 resulted in the reduction of CD133+ population that contribute to the stemness of liver cancer cells." (PMID 37202772, 2023). "Two FOXM1 proteolysis-targeted chimeras (PROTACs) have been reported recently that degrade FOXM1 and inhibit breast and liver cancer cell proliferation and xenograft growth when dosed IV." (PMID 37370117, 2023). "Changes in FOXM1 expression can influence the functionality of the immune system, potentially driving the onset and progression of liver cancer." (PMID 37817774, 2023). "According to TCGA database, FOXM1 showed notable differences between tumor and normal tissue in liver cancer." (PMID 37202772, 2023). "Then, we further confirmed the high expression of FOXM1 and PD-L1 by immunohistochemical staining of tumor tissues and paracancerous tissues in five liver cancer patients." (PMID 36171633, 2022). "Conversely, inhibition of FOXM1 in liver cancer cells reduced cell proliferation, angiogenesis, and EMT." (PMID 35887129, 2022). "Our findings have identified FoxM1 as an important inhibitory target of Artemisinin in hepatic cancer cells." (PMID 34900697, 2021). "In our study, we have identified the antimalarial natural product, Artemisinin, to efficiently curb FoxM1 expression and activity in hepatic cancer cells, thereby exhibiting potential anticancer efficacy." (PMID 34900697, 2021). "In SNU-739, a liver cancer cell line, although there is a high level of FoxM1, the expression of STMN1 is very low, whereas in Colo-320 a CRC cell line, a low level of FoxM1 is accompanied with a high level of STMN1." (PMID 33526768, 2021). "Of note, high expression of FoxM1 and its downstream effector factors (Plk1, CyclinB1, Skp2 and Aurora B Kinase) correlated with poor overall survival in hepatic cancer patients (analyzed from RNA-seq data available on Kaplan-Meier plotter)." (PMID 34900697, 2021). "Many studies have revealed that FOXM1, a carcinogenic transcriptional factor, has a critical function in the pathogenesis of various cancers, including liver cancer." (PMID 32308683, 2020).
liver cancer (continued). "Several studies have shown that targeting FoxM1 is an effective therapeutic approach against liver cancer, and FoxM1 downregulation or inactivation leads to inhibition of proliferation, migration and invasion of various cancer cells." (PMID 31986488, 2020). "Our study clearly demonstrated that FOXM1 is a direct functional target of miR-34a in liver cancer cells." (PMID 32308683, 2020). "This novel DNMT1/miR-34a/FOXM1 signaling-mediated mechanism of stemness acquisition and maintenance in liver cancer offers a new potential therapeutic strategy for the treatment of human liver cancer." (PMID 32308683, 2020). "Genome-wide association studies have proposed several putative molecules for liver cancer prognosis, for example, Forkhead box M1 (FoxM1), a major modulator of tumorigenesis in various cancers, including liver cancer." (PMID 32308683, 2020). "FOXM1 expression is relatively low in quiescent cells but elevated in most tumors including liver cancer." (PMID 31072351, 2019). "In summary, the present study demonstrated that HGK is effective against liver cancer, and that its tumor suppression mechanism is at least partly modulated by its miR-320a-mediated inhibition of both FOXM1 expression and EMT." (PMID 31877715, 2019). "Accordingly, POH1 deletion substantially inhibited the expression of Survivin and FOXM1 proteins in human liver cancer cell lines." (PMID 26510456, 2015). "The POH1-mediated regulation of E2F1 expression strengthens E2F1-downstream prosurvival signals, including upregulation of Survivin and FOXM1 protein levels, and efficiently facilitates tumour growth of liver cancer cells in nude mice." (PMID 26510456, 2015). "In this study, we demonstrated that the thiazole antibiotics inhibit FoxM1 transcriptional activity, they also downregulate FoxM1 expression and induce cell death in neuroblastoma, leukemia and liver cancer cells." (PMID 19440351, 2009). "We found that both Siomycin A and thiostrepton repress FoxM1 protein expression, and induce apoptosis in these leukemia and liver cancer cells." (PMID 19440351, 2009). "Consistent with its role in promoting proliferation, elevated expression of FOXM1 has recently been reported in a variety of human tumour entities including breast and liver cancer." (PMID 18254960, 2008). "METase could inhibit autophagy through regulating the highly up-regulated in liver cancer (HULC)/Forkhead box protein M1 (FoxM1) pathway and enhance resistant cell sensitivity to cisplatin." (PMID 40052129, 2025). "Precious studies have suggested that FOXM1 overexpression was associated with tumor progression in patients with clear cell renal cell carcinoma, and FOXM1 silence could lead to liver cancer cell growth and a decline of CDK2 expression." (PMID 38342795, 2024). "In addition, FOXM1, a pivotal regulator of cell cycle progression, aids stemness maintenance in CSCs by supporting translocation of β-catenin to nucleus in liver cancer cells." (PMID 37202772, 2023). "FOXM1 modulates epithelial-mesenchymal transition by targeting Snai1 in liver cancer." (PMID 35680842, 2022). "The two segments of FOXM1-PROTAC, in the presence of FOXM1 and E3 ubiquitin ligase, assist the ubiquitination and degradation the FOXM1 protein, thereby inhibiting the proliferation of liver cancer cells, further decreasing the expression of GLUT1 and PD-L1, and reducing glucose metabolism." (PMID 36171633, 2022). "In addition, other studies have found that the metabolism of fatty acid oxidation (FAO) in liver cancer cells is active, and the activation of transcription factor FOXM1 can promote tumorigenesis." (PMID 35655758, 2022). "FOXM1 promotes proliferation in liver cancer cells through transcriptional upregulation of CCNB1." (PMID 35680842, 2022).
liver cancer (continued). "Moreover, Artemisinin, when used in combination with Thiostrepton, an established FoxM1 inhibitor, markedly reduced anchorage-independent growth and displayed more pronounced death in liver cancer cells." (PMID 34900697, 2021). "Considering that Artemisinin compounds are in current clinical use with favorable safety profiles, the results from our study will potentiate its utility in juxtaposition with established FoxM1 inhibitors, promoting maximal therapeutic efficacy with minimal adverse effects in liver cancer patients." (PMID 34900697, 2021). "Another study also suggested that OTUB1 mediates Forkhead Box M1 (FOXM1) in liver cancer cells." (PMID 34773364, 2021). "Whether DNA methyltransferase 1 (DNMT1)/miR-34a/FoxM1 signaling promotes the stemness of liver cancer stem cells (LCSCs) remains unclear." (PMID 32308683, 2020). "In addition, we and others have shown that FOXM1 is a key regulator of stemness in various cancers, including liver cancer." (PMID 32308683, 2020). "Furthermore, VP-mediated inhibition of YAP downregulated FOXM1 and CTGF, and suppressed YAP/TEAD4/FOXM1-dependent activation of CIN-related genes in liver cancer and synovial sarcoma cells." (PMID 33178014, 2020). "This study aimed to assess whether methylation-based silencing of miR-34a by DNMT1 contributes to stemness features via FoxM1 upregulation in liver cancer cells." (PMID 32308683, 2020). "Therefore, HGK can potentially be used in the treatment of other cancers that exhibit FOXM1 overexpression in addition to liver cancer." (PMID 31877715, 2019). "FoxM1 is essential in the progression of Ras signaling-driven liver cancer." (PMID 30580327, 2018). "In this study, we found Nrf2 was transcriptionally activated by FoxM1, and Prx I was activated by the H-rasG12V/pERK/FoxM1/Nrf2 pathway and suppressed ROS-induced hepatic cancer-cell death along with formation of a positive feedback loop with Ras/ERK/FoxM1/Nrf2 to promote hepatic tumorigenesis." (PMID 27517622, 2016). "Furthermore, E2F1 inhibition by siRNAs almost entirely abolished POH1-mediated upregulation of Survivin and FOXM1 in liver cancer cells." (PMID 26510456, 2015). "FOXM1 is one of these candidate genes and has been selected for further analysis because chemical inhibitors of this target molecule are already available and have been shown to limit proliferation e.g. in liver cancer cells in vivo." (PMID 18254960, 2008). "However, the relationship between FOXM1 and regorafenib resistance in liver cancer cells remains unknown." (PMID 35887129, 2022). "Considering the role of FOXM1 in proliferation and AFP expression in AFP-positive HCC cells, it is possible that the inhibition of FOXM1 with a very low concentration of carfilzomib might be therapeutically effective to suppress the proliferation of AFP-positive liver cancer stem cells." (PMID 35955438, 2022). "However, it is currently unknown whether low miR-34a expression followed by FoxM1 overexpression participates in enriching LCSCs and promoting stemness features in liver cancer cells." (PMID 32308683, 2020). "In addition, elevated FoxM1 is tightly related to unfavorable prognosis in liver cancer." (PMID 32308683, 2020). "Previous studies have indicated that the transcription factor FOXM1 regulates the expression of many other oncogenes; it is also considered an important target for anticancer therapy as it is overexpressed in various malignancies including lung, breast, and liver cancers." (PMID 31877715, 2019). "Additionally, the expression of the EMT-associated genes, namely snail and N-cadherin were also obviously decreased, providing further evidence that HGK suppresses the growth of liver cancer cells by inhibiting the expression of FOXM1 and its downstream EMT-related genes." (PMID 31877715, 2019). "However, FOXM1 could activate c-myc promoter and promote the proliferation of liver cancer cells." (PMID 41179299, 2025).
liver cancer (continued). "We found that LXR alpha and high expression of liver cancer transcript (highly upregulated in liver cancer, HULC) cut the HULC promoter region, combining expression, thereby lowering fork frame M1 (FOXM1) expression." (PMID 41179299, 2025). "FOXM1 PROTAC resulted in FOXM1 degradation and reduced the viability of breast, lung, colon, and liver cancer cells." (PMID 38791105, 2024). "Their insights into the mechanism revealed FOXM1’s role in promoting liver cancer cell invasion and metastasis by upregulating MMP-7, RhoC, and ROCK1, with HBx further amplifying FOXM1 expression through the ERK/CREB pathway." (PMID 37817774, 2023). "YAP/TEAD4 also binds FOXM1 (Forkhead Box M1) to induce the chromosome instability and targets PAI-1 (plasminogen activator inhibitor-1) to control the senescence in liver cancer." (PMID 35602596, 2022). "Here, we first analyzed the expression of FOXM1, GLUT1 and PD-L1 in liver cancer through database and clinical samples of patients." (PMID 36171633, 2022). "Thirdly, FoxM1 plays an essential role in HCC cell migration, invasion, as well as liver cancer progression and in cancer cells with stem cell features." (PMID 27351282, 2016). "FOXM1-PROTAC also decreased migration and colony formation of breast and liver cancer cells." (PMID 38791105, 2024). "Thus, we examined the role of FOXM1 in the establishment of the CSC characteristics and regorafenib resistance via CD44 using the HepG2 and Hep3B liver cancer cell lines." (PMID 35887129, 2022). "Among them, typical liver cancer stem cell markers such as AFP and keratin 19 (KRT19) were upregulated in FOXM1-high HCC, whereas typical mature hepatocyte markers such as solute carrier organic anion transporter family member 1B1 (SLCO1B1) and cytochrome P450 3A4 (CYP3A4) were downregulated." (PMID 35955438, 2022). "It has been found that crosstalk between FOXM1/NF‐κB and MAT1A (methionine adenosyl transferase 1A) may affect tumorigenesis in liver cancer, but little is known about MAT1A in GBC." (PMID 33718182, 2021). "FOXM1, cooperating with YAP, was found to contribute to chromosome instability in liver cancer." (PMID 31851620, 2019). "Altogether, these results, strongly confirm that knock-out of IQGAP1/FOXM1 with sgIF loaded HLC9-EVs + sorafenib in effect reduces CD133+ CSCs and reverses sorafenib resistance, and hence stands as promising novel therapeutic approach for thriving liver cancer treatments in the future." (PMID 37202772, 2023).
lung adenocarcinoma (62 papers, 2009 to 2025). A carcinoma that arises from the lung and is characterized by the presence of malignant glandular epithelial cells. "Taken together, our study revealed that the high-risk histological subtype-related FAM83A hijacks FOXM1 transcriptional regulation to promote malignant progression in lung adenocarcinoma, which implies targeting FAM83A/FOXM1 is the therapeutic vulnerability." (PMID 37904848, 2023). "We found that HMGA1 and FOXM1 were associated with poor prognosis for three cancers with high morbidity and mortality, namely lung adenocarcinoma (LUAD), liver hepatocellular carcinoma (LIHC) and pancreatic adenocarcinoma (PAAD)." (PMID 37240870, 2023). "FOXM1 is a transcription factor that belongs to the forkhead transcription factor family, and it is one of the key transcriptional regulators linked to lung adenocarcinoma." (PMID 36291764, 2022). "Since overexpression of FOXM1 is associated with poor patient survival in lung adenocarcinoma, we selected FOXM1 for further examination." (PMID 36291764, 2022). "Among the activated transcriptional regulators, CENPA, MYBL2, and FOXM1 were linked to numerous cancer-specific enhancers and high expression of these regulators was observed in a subgroup of lung adenocarcinomas showing poor patient survival." (PMID 32925947, 2020). "In the present study, we established that TOPO-2α expression was significantly decreased in Foxm1 deficient lung tumors as well as in A549 human lung adenocarcinoma cells transfected in vitro with Foxm1-specific siRNA." (PMID 19672312, 2009). "Taken together, these data suggest that activation of FoxM1 is increased in KRAS mutant lung adenocarcinomas retaining the WT KRAS allele and that downregulation of its transcriptional activity may represent a therapeutic target for this group of patients." (PMID 34573384, 2021). "However, the molecular mechanisms underlying FOXM1-mediated gefitinib resistance in lung adenocarcinoma cells remains to be elucidated." (PMID 27494877, 2016). "Among the remaining factors, we selected FOXM1 for further analysis, with TCGA data indicating that FOXM1 is highly expressed in lung adenocarcinoma and patients with a high expression have a poor prognosis." (PMID 41413918, 2025). "FOXM1-depleted mice display significantly compromised tumor growth and metastasis, whereas FOXM1 overexpression contributes to poor prognosis in patients with lung adenocarcinomas, meningioma and acute lymphoblastic leukemia." (PMID 39060421, 2024). "MYBL2 and FOXM1 were related to cancer-specific enhancers, and its high expression in lung adenocarcinomas has been related to poor patient survival." (PMID 36661515, 2023). "The areas under the ROC curve (AUC) of the prognostic model showed that HMGA1 and FOXM1 had moderate discrimination performance in lung adenocarcinoma patients with 1- and 3-year OS (overall survival), and poor discrimination in 5-year OS." (PMID 37240870, 2023). "The abundance of m6A in FOXM1 transcripts was increased after the knockdown of ALKBH5 in lung adenocarcinoma cells, resulting in a reduction of FOXM1 translation and diminished cell proliferation and invasion." (PMID 37007161, 2023). "This indicates that treatment with FDI-6 can reduce the activities of FOXM1 as well as MYBL2 in nuclei of the lung adenocarcinoma cells." (PMID 36291764, 2022). "Overall, our findings suggest that MYBL2 and FOXM1 activate cell cycle genes together, acting as oncogenic transcription factors in lung adenocarcinoma cells, and they are potential treatment targets for the disease." (PMID 36291764, 2022). "To characterize the molecular mechanisms of FOXM1 in lung adenocarcinoma cells, we profiled the genome-wide binding sites of FOXM1 in A549 cells using ChIP-seq." (PMID 36291764, 2022). "For example, we showed that CENPA is one of the key targets of MYBL2 and FOXM1 in lung adenocarcinoma cells." (PMID 36291764, 2022).